APOB (apolipoprotein B)
Diseases named in the same sentence as APOB in open-access papers (continued):
Sharing a sentence is not in itself a finding about the gene and the disease.
hypothyroidism (12 papers, 2005 to 2025). Abnormally low levels of thyroid hormone. "As a result, hypothyroidism can be associated with increased serum levels of cholesterol, triglycerides, low-density lipoprotein and apolipoprotein B." (PMID 39997750, 2025). "This could be due to the reason that selenium deficiency leads to decreased T3 levels and inturn hypothyroid state through decreased expression of 5'-DI enzyme, further hypothyroidism has been associated with increased level of apoB." (PMID 16271152, 2005). "Studies consistently report elevated serum levels of total cholesterol (TC), LDL-C, apolipoprotein B, lipoprotein (a), and potentially triglycerides (TGs) in individuals with hypothyroidism." (PMID 38741822, 2024). "The levels of TSH, hsCRP, IL-10, IL-6, TNF-α, TC, LDL, FFA and ApoB in the pregnancy hypothyroidism group were higher than those in the control group (P <0.05)." (PMID 36275023, 2022). "The concentrations of TC, LDL, FFA and ApoB in pregnant women with clinical hypothyroidism were significantly higher than those in the control group." (PMID 36275023, 2022). "Patients with hypothyroidism often present with abnormal blood lipid profiles, characterized by elevated levels of low-density lipoprotein cholesterol (LDL-C), TGs, and apolipoprotein B (ApoB)." (PMID 39872142, 2024). "Overt hypothyroidism is often accompanied by increased TC, LDL, apolipoprotein B, lipoprotein A, and TG levels, but such alterations on lipidemic profile are usually not apparent in subclinical hypothyroidism." (PMID 34946319, 2021). "In patients with overt hypothyroidism, there is an increase in serum TC, LDL-C, apolipoprotein B, lipoprotein (a) and TG levels." (PMID 25541895, 2014). "Hypothyroidism, on the other hand, is characterized by elevated total cholesterol, increased LDL, normal or increased HDL cholesterol, and normal or increased TG levels, due to decreased cholesterol excretion, decreased LDL turnover, and increased ApoB levels." (PMID 40937266, 2025). "Another hypothesis is that hypothyroidism may contribute to maternal lipid abnormalities, such as high cholesterol, elevated low-density lipoprotein (LDL), and increased apolipoprotein B (apo B), which can negatively affect birth weight." (PMID 41393295, 2025). "Also other studies indicate that elevated apoB are not necessarily directly involved in sdLDL pathogenesis in hypothyroidism." (PMID 25300222, 2014).
psoriasis (12 papers, 2018 to 2025). An autoimmune condition characterized by red, well-delineated plaques with silvery scales that are usually on the extensor surfaces and scalp. "As patients with psoriasis have a greater risk of developing cardiovascular diseases, ApoB has been demonstrated as a better predictor for cardiovascular disease risk compared to LDL." (PMID 37375611, 2023). "The percentages of the mediatory effect of LDL cholesterol, apolipoprotein B, and lipoprotein A under psoriasis conditions on MI risk was 7.4%, 10.2%, and 4.1%, respectively." (PMID 37755256, 2023). "Present findings agree with the positive association reported for the ApoB/ApoA-I ratio with cIMT, suggested as a suitable tool for early detection of premature atherosclerosis in psoriasis patients." (PMID 29535705, 2018). "The authors concluded that the ApoB/ApoA1 ratio is the best predictor of CVD risk in psoriasis." (PMID 40137160, 2025). "Moreover, it was established that LDL cholesterol, ApoB, and lipoprotein (a) mediate the effect of psoriasis on the risk of myocardial infarction." (PMID 40137160, 2025). "Moreover, it was observed that LDL cholesterol, apolipoprotein B, and lipoprotein A mediated the psoriasis effect on MI risk." (PMID 37755256, 2023). "The aim of this study was to evaluate the potential associations between serum concentrations of apolipoproteins (ApoA1, ApoA2, ApoB, ApoC1, ApoC3, ApoD, ApoE, ApoH, and ApoJ) and various clinical and biochemical markers in patients with psoriasis." (PMID 40137160, 2025). "Until now, most research on apolipoproteins in psoriasis has focused on ApoA1 and ApoB, primarily because of their well-established roles in cardiovascular risk and lipid metabolism." (PMID 40137160, 2025). "While limited prior research has primarily focused on apolipoproteins such as ApoA1, ApoA2, ApoB, ApoC1, ApoC3, and ApoE in psoriasis, our study uniquely extends this scope by also evaluating ApoD, ApoH, and ApoJ in this patient population for the first time." (PMID 40137160, 2025). "No significant genetic correlation and causal relationship was found between lipidemic traits (HDL, LDL, TG, TC, apoA1, apoB, apoE) and psoriasis." (PMID 38550599, 2024). "Two meta-analyses highlighted that LDL cholesterol, lipoprotein A, and apolipoprotein B levels were considerably higher in individuals with psoriasis than in controls." (PMID 37755256, 2023). "In conclusion, inflammation in psoriasis can increase serum hCRP levels, resulting in the reduction of anti-atherogenic lipid ApoA1 and increase of pro-atherogenic lipid ApoB." (PMID 34996506, 2022). "While ApoA1 and ApoB in psoriasis have been the primary focus of research due to their established roles in lipid metabolism and cardiovascular risk, other apolipoproteins, such as ApoA2, ApoC1, ApoC3, ApoD, ApoE, ApoH, and ApoJ, have not been widely studied in psoriasis." (PMID 40137160, 2025). "Similarly, as for the shared SNPs between apoB and psoriasis, the most significant one was also rs184114817 (pCAPSSOC=1.00×10-10)." (PMID 38550599, 2024). "Furthermore, the direct effect of psoriasis on MI was also attenuated in the multivariable psoriasis–apolipoprotein B–MI MR (OR: 1.029, 95% CI: 1.017–1.041, p = 0.046)." (PMID 37755256, 2023). "This MR study indicated a causal association between genetically determined psoriasis and an elevated risk of lipid metabolism levels and MI, with evidence that the LDL cholesterol, apolipoprotein B, and lipoprotein A mediated the effect of psoriasis on the MI risk." (PMID 37755256, 2023). "The ratio of ApoB to ApoA1 was significantly downregulated in male patients with psoriasis after MTX treatment, indicating that the role of MTX on CVD and other concomitant diseases might be related to sex." (PMID 34996506, 2022). "The F-statistic value for the instrument–psoriasis link was 15.996 in the HDL, LDL, apolipoprotein A1, and apolipoprotein B model and 16.533 in the lipoprotein A model." (PMID 37755256, 2023).
psoriasis (continued). "Stepwise regression analysis found a positive correlation between the inflammatory marker hCRP and the Psoriasis Area Severity Index (PASI), ApoB/ApoA1 ratio, BMI, and smoking." (PMID 34996506, 2022). "The effect of psoriasis on MI was decreased when the current investigation involved an adjustment for lipid metabolism traits in the multivariable MR model, indicating that LDL cholesterol, apolipoprotein B, and lipoprotein A were the intermediate factors." (PMID 37755256, 2023). "Regarding lipidemic traits, we did not observe any significant genetic correlation with psoriasis (apoA1: rg=-0.03, p=0.261; apoB: rg=-0.02, p=0.615; apoE: rg=0.09, p=0.721; HDL: rg-0.05, p=0.077; LDL: rg=-0.04, p=0.344; TC: rg=0.08, p=0.164; TG: rg=0.06, p=0.053)." (PMID 38550599, 2024). "Therefore, the decrease of ApoB, TC, and Lp(a) by MTX was not related with sex and psoriasis subtype." (PMID 34996506, 2022).
rheumatoid arthritis (12 papers, 2010 to 2025). A chronic, systemic autoimmune disorder characterized by inflammation in the synovial membranes and articular surfaces. "In adult patients with rheumatoid arthritis, changes in apolipoprotein B (Apo B) concentrations and the Apo B/apolipoprotein A-I (Apo A-I) ratio were compared to those in the classical lipid profile have been independently associated with cardiovascular risk." (PMID 33941215, 2021).
viral infections (12 papers, 2014 to 2025). "Apolipoprotein B mRNA editing catalytic polypeptide like (APOBEC) proteins are associated with protecting mammalian cells from viral infections." (PMID 38473423, 2024). "The mammalian apolipoprotein B mRNA-editing enzyme catalytic polypeptide-like 3 (APOBEC3 or A3) family of cytidine deaminases restrict viral infections by mutating viral DNA and impeding reverse transcription." (PMID 33465707, 2021). "It usually represents a defense raised by the host cells to suppress viral infection through the APOBEC (Apolipoprotein B mRNA Editing Catalytic Polypeptide-like) family." (PMID 36298851, 2022). "Many studies investigated the genetic association between APOB and HCV-related viral disease showing that variants in APOB increase the susceptibility to HCV infection." (PMID 32443539, 2020). "The apolipoprotein B mRNA editing enzyme, catalytic polypeptide-like (APOBEC) family of DNA cytosine deaminases provides a broad and overlapping defense against viral infections." (PMID 33671095, 2021). "The apolipoprotein B messenger RNA-editing, enzyme-catalytic, polypeptide-like 3 (APOBEC3) family of cytidine deaminases plays an important role in the innate immune response to viral infections by editing viral genomes." (PMID 28825669, 2017).
gallstones (10 papers, 2013 to 2026). Solid crystalline precipitates in the biliary tract, usually formed in the gallbladder, resulting in the condition of cholelithiasis. "Combination therapy with simvastatin and ezetimibe reduces plasma levels of remnant cholesterol, apolipoprotein B/lipoprotein, triglycerides, and cholesteryl esters in patients with gallstones, potentially due to the anti-inflammatory effects of statins." (PMID 37111293, 2023). "Other mutations and alterations have been described in different genes and proteins potentially involved in a higher risk of developing gallstones, such as ABCB11, cholesterol 7a-hydroxylase (CYPA1), APOB gene, and cholecystokinin A receptor (CCKAR)." (PMID 35207722, 2022). "Serum lipid levels are significantly abnormal in patients with gallstones, including levels of triglycerides (TG), high-density lipoprotein cholesterol (HDL), low-density lipoprotein cholesterol (LDL), and apolipoprotein B (APOB)." (PMID 37888101, 2023). "A concomitant ninefold increase of apolipoprotein B was found, suggesting secretion of triglyceride-rich lipoproteins (TRLs) at the canalicular pole of the hepatocyte in livers from nonbariatric gallstone patients." (PMID 34677397, 2021). "The concentration of apoA-1 did not significantly differ (5.3 vs. 5.9 mg/dL; p = 0.47), while a ninefold lower median concentration of apoB was found in bariatric gallstone patients compared to nonbariatric gallstone patients (1.6 vs. 18.8 mg/dL; p < 0.0001)." (PMID 34677397, 2021). "One population-based study in China recruited 2,068,523 patients, and reported that all the serum lipid levels including total cholesterol, TG, HDL cholesterol, LDL cholesterol and apolipoprotein B were significantly different between patients with or without gallstones." (PMID 37888101, 2023).
prediabetes (10 papers, 2013 to 2025). "The present results are highly consistent with a study conducted in China that showed a strong association between the mean ApoB/ApoA1 ratio and prediabetes." (PMID 39081429, 2024). "However, to our current understanding, there have been limited studies that have identified an independent association between the ApoB/ApoA1 ratio and lipoprotein ratio with glycemic levels in individuals with prediabetes." (PMID 39081429, 2024). "Consequently, the mean ratio of ApoB/ApoA-I was positively associated with prediabetes." (PMID 39081429, 2024). "Participants in the highest ApoB quartile had 53% higher odds of prediabetes (adjusted OR = 1.53; 95% CI: 1.22–1.91; p < 0.001) compared to the lowest quartile." (PMID 40423035, 2025). "ApoB levels were significantly increased in individuals with prediabetes, while the levels of ApoA-I showed the opposite trend." (PMID 39081429, 2024). "The mean level of LDL-C/HDL-C ratio (2.34±0.98) was significantly higher, whereas ApoB/ApoA ratio was insignificantly higher in prediabetes individuals with HOMA-IR ≥2.5 compared to those with HOMA-IR <2.5." (PMID 39081429, 2024). "A strong correlation was found between the ApoB/ApoA1 ratio and glycemic levels in individuals with prediabetes." (PMID 39081429, 2024). "Individuals with prediabetes exhibited significantly higher mean levels of Lp(a), mean ApoB/ApoA1 ratio, and mean LDL-C/HDL-C ratio compared to apparently healthy individuals." (PMID 39081429, 2024). "Moreover, Lp(a), LDL-C/HDL-C ratio, and ApoB/ApoA ratio were significantly higher among individuals with prediabetes." (PMID 39081429, 2024). "In addition, we examined changes in concentrations of lipids and apolipoprotein B among participants with prediabetes and normoglycemia." (PMID 23360385, 2013). "A significant decrease in the prevalence of the lipid triad consisting of low concentrations of high-density lipoprotein cholesterol and elevated concentrations of triglycerides and apolipoprotein B was noted among participants with prediabetes and normoglycemia." (PMID 23360385, 2013). "Consequently, the objective of this study is to evaluate the ApoB/ApoA1 ratio and LDL-C/HDL-C ratio in prediabetes in relation to glycemic levels and establish the association between apolipoprotein and lipoprotein ratios in prediabetic individuals and their glycemic levels." (PMID 39081429, 2024). "This study observed that the Lp (a), ApoB/ApoA-I ratio, and LDL-C/HDL-C ratio were closely correlated with serum glucose, blood HbA1C, and HOMA-IR in individuals with prediabetes." (PMID 39081429, 2024). "There was a significant high mean level of Lp(a), mean ApoB/ApoA1 ratio, and mean LDL-C/HDL-C ratio in individuals with prediabetes compared to apparently healthy individuals." (PMID 39081429, 2024).
coronary artery calcification (9 papers, 2017 to 2026). Calcification of the coronary artery, used as a measure of coronary atherosclerosis, a risk factor for myocardial infarction. "The R3500Q (rs5742904) mutation in ApoB was found to be a major determinant of LDL levels and coronary artery calcification in the Amish population." (PMID 28086795, 2017). "ApoB R3500Q polymorphism may increase CAD risk by elevating LDL levels and coronary artery calcification (CAC)." (PMID 35330428, 2022). "Our study showed that the predictive value of apolipoprotein B/A-I ratio for coronary artery calcification may differ according to kidney function." (PMID 28957410, 2017). "The mean apolipoprotein B/A-I level was significantly higher in the participants with coronary artery calcification than in the participants without coronary artery calcification." (PMID 28957410, 2017).
hyperthyroidism (9 papers, 2005 to 2024). Overactivity of the thyroid gland resulting in overproduction of thyroid hormone and increased metabolic rate. "An example is apolipoprotein B (APOB)–E05 thyrotoxicosis (hyperthyroidism) association which achieved P = 9.02 × 10−9 in pan-ancestry analysis but had borderline significance (P = 1.77 × 10−8) in EUR-specific analysis." (PMID 39261665, 2024). "Lower triglycerides, HDL, apoA1, apoB, and Lp(a) levels have been found in patients with hyperthyroidism compared with euthyroid controls, which is questionable by other reports." (PMID 21789282, 2011). "It has been reported that patients with hyperthyroidism are shown lower serum levels of VLDL-, LDL-, and HDL-cholesterols, apolipoprotein B (apoB), lipoprotein-α (Lpα) and proproteinconvertasesubtilisin/kexin type 9 (PCSK9)." (PMID 29246135, 2017). "Both hyperthyroidism and eprotirome treatment reduced circulating PCSK9, lipoprotein cholesterol, apoB and AI, and lipoprotein(a), while cholesterol synthesis was stable." (PMID 25172631, 2014). "The serum concentration of total cholesterol, LDL-C, non-HDL-C, triglycerides, apoA-1 and apoB were unchanged in subclinical hyperthyroidism." (PMID 32300332, 2020). "Levels of apoB and apoCIII, mainly produced in the liver, showed similar changes in the two TH exposure models, whereas apoAII and apoAIV that are predominantly from the small intestine were increased in hyperthyroidism but not eprotirome-treated subjects." (PMID 25172631, 2014). "Treatment of overt hyperthyroidism resulted in significant increases in Lp(a) by 4.18 mg/dL (95% CI: 1.65, 6.71)., TC, LDL-C, HDL-C, apoA and apoB concentrations without affecting triglycerides." (PMID 35606076, 2022).
Hypocholesterolemia (9 papers, 2016 to 2025). An decreased concentration of cholesterol in the blood. "A role for SURF4 in APOB secretion was further supported by a recent study in which acute deletion of hepatic Surf4 in adult mice caused hypocholesterolemia and a reduction in hepatic lipoprotein secretion." (PMID 36193893, 2022). "A very low plasma cholesterol level, or hypocholesterolemia, is usually defined as persistent plasma total cholesterol, LDLc, and apoB concentrations below the 5th percentile of the reference population." (PMID 34829957, 2021). "Based on the available SNP genotyping data, this was linked to a region on BTA11 and the fact that the affected calves suffer from hypocholesterolemia suggested APOB as positional and functional candidate for this haplotype, i. e. cholesterol deficiency." (PMID 27128314, 2016). "Patients had hypocholesterolemia depicted by lower levels of total cholesterol, HDL-C, LDL-C, as well as Apolipoprotein A1 and Apolipoprotein B compared to controls." (PMID 31861992, 2019).
mixed hyperlipidemia (9 papers, 2009 to 2025). "In a double-blind study of 48 patients with mixed hyperlipidemia, the human ANGPTL3/8 mAb reduced plasma TG levels by 70%, remnant cholesterol levels by 61%, LDL cholesterol levels by 36%, and APOB levels by 31%, while increasing HDL cholesterol levels by 26%." (PMID 37824203, 2023). "It is also worth noting that although apoB was not markedly elevated in HLP3 like it has been described for familial combined hyperlipidemia, it was modestly increased in at least some subjects." (PMID 35910208, 2022). "The significant reductions of atherogenic lipids including LDL-C, non–HDL-C, and apolipoprotein B seen with evolocumab are similar in patients with and without mixed hyperlipidemia." (PMID 27240673, 2016).
peripheral artery disease (9 papers, 2013 to 2025). "The primacy of apoB as a risk determinant for ASCVD was confirmed in another Mendelian randomization analysis, which also demonstrated that apoB was the most significant lipid-related causal factor for peripheral arterial disease." (PMID 36012684, 2022). "However, our results adjusted for apolipoprotein B suggest that only the association between elevated remnant cholesterol and increased risk of peripheral artery disease could be explained by a higher particle number." (PMID 37776347, 2023).